RNU6-925P (RNA, U6 small nuclear 925, pseudogene)
Gene: Small nuclear RNA gene on chromosome 8 (89,900,721 to 89,900,824, reverse strand). Ensembl gene ENSG00000207359.
Homologues: Orthologues: chimpanzee U6 (100% identical), macaque U6 (87% identical), rabbit U6 (81% identical). Paralogues in human: RNU6-46P (89% identical), RNU6-1011P (88% identical), RNU6-1 (88% identical), RNU6-1117P (88% identical), RNU6-15P (88% identical), RNU6-19P (88% identical), RNU6-2 (88% identical), RNU6-33P (88% identical), RNU6-38P (88% identical), RNU6-39P (88% identical), RNU6-3P (88% identical), RNU6-480P (88% identical), and 1287 more.